CPEB2-DT (CPEB2 divergent transcript)
Synonyms: DRAIR; CPEB2-AS1
Gene: Long non-coding RNA gene on chromosome 4 (14,909,961 to 15,002,337, reverse strand). Ensembl gene ENSG00000247624.
Diseases named in the same sentence as CPEB2-DT in open-access papers:
CPEB2-DT is named in the same sentence as 8 diseases in open-access papers, as found by Europe PMC text mining. Sharing a sentence is not in itself a finding about the gene and the disease.
CPEB2-DT shares sentences with these, for which no sentence is quoted: diabetes (4 papers); type 2 diabetes mellitus (3); atherosclerosis (1); cancer (1); cardiovascular disorder (1); lymph node metastasis (1); triple-negative breast carcinoma (1); tumor (1).